MMP9 (matrix metallopeptidase 9)
Diseases named in the same sentence as MMP9 in open-access papers (continued):
Sharing a sentence is not in itself a finding about the gene and the disease.
breast carcinoma (continued). "Through microdialysis, they found increased endostatin and MMP-2 and MMP-9 levels in mice with breast cancer treated with tamoxifen, and inhibition of MMP-2 and MMP-9 resulted in a significant decrease in endostatin levels." (PMID 32669083, 2020). "With respect to the anti-cancer effect, DHA treatment was reported to inhibit MMP-9 expression in human breast cancer cells, MCF-7." (PMID 33381031, 2020). "Recent reports have identified the interaction of RUNX2 with CD44-ICD on the promoter of the MMP-9 gene in breast cancer." (PMID 33062960, 2020). "Complementarily, Rsv decreased other genes associated with the EMT, such MMP9 and MMP2, which are involved in the aggressiveness and invasiveness of Doxo-resistant breast cancer." (PMID 33204396, 2020). "The role of MMP-9 in metastasis and invasion in cancers including prostate cancer, colorectal cancer, and breast cancer is well-known, and previous publications have shown that MMP-9 directly contributes to cancer metastasis and invasion." (PMID 32328465, 2020). "LARP6 expression is elevated in breast cancers; such cancers show especially aggressive phenotypes due to the upregulations of MMP9 and VEGF." (PMID 32967226, 2020). "The reduction in MMP-9 protein levels reserved the invasion abilities of the breast cancer cell lines." (PMID 32178324, 2020). "The combination of brazilin and doxorubicin has also been shown to inhibit metastasis in HER2-positive breast cancer through downregulation of MMP9, MMP2, and Rac1." (PMID 32986377, 2020). "APE can decrease miR-18a and MMP-9 expressions and increase Dicer1 expression in rat mammary cancer." (PMID 32458624, 2020). "The selective MMP-9 inhibition resulted in inhibition of cellular migration in a mammary tumor model and mammary tumor growth and metastasis in an orthotopic xenograft." (PMID 32466129, 2020). "Gelatinase MMP-9 is a crucial enzyme that induces migration and invasion in breast cancer cells (Radisky and Radisky, 2015)." (PMID 31611756, 2019). "Overexpression of MMP‐9 increases the malignancy of breast cancer cell lines, largely via activation of the TGF‐β/SMAD signalling." (PMID 31264317, 2019). "TNF-α enhances the fusion of breast cancer cells and epithelial cells by upregulating the expression of MMP-9 in cancer or epithelial cells." (PMID 31380426, 2019). "FFE reduced the phosphorylation of AKT without affecting the expression levels of the total AKT protein and reduced the expression of MMP-9 in MDA-MB-231 breast cancer cells." (PMID 30845749, 2019). "The present study suggests that MPPa-PDT inhibited the migration and invasion of breast cancer cells through the Akt/NF-κB-dependent MMP-9 signaling pathway by upregulating ROS production." (PMID 31783821, 2019). "Relatively higher expression of BMAL1 was identified in MDA-MB-231 cells than in T47D and ZR-75-30 cells, consistent with the expression of MMP9 in breast cancer cells." (PMID 31346317, 2019). "Based on these observations, we next examined the role of MMP2 and MMP9 in IL-6-induced breast cancer cell migration." (PMID 31409371, 2019). "Experimental evidence suggests that MMP-2 and MMP-9 also contribute to the initiation and progression of breast cancer by cleaving and activating diverse proteins involved in angiogenesis, invasion and metastasis." (PMID 31554180, 2019). "It suggests the enhanced invasion ability of the breast cancer cells by overexpressing MMP‐9 relies largely on the activation of TGF‐β/SMAD signal pathway." (PMID 31264317, 2019). "Among the several MMP family members, MMP-2 and MMP-9 were highly expressed in invasive breast cancer cells." (PMID 31068208, 2019). "In particular, MMP-2 and MMP-9 degrade type IV collagen and promote the rupture of basal membranes in colorectal, prostate, lung and breast cancers." (PMID 31671408, 2019). "Oro-A can inhibit migration by suppressing the expression of MMP-2 and MMP-9 on human breast cancer cells." (PMID 30871117, 2019).
breast carcinoma (continued). "Specifically, RUNX2 has been shown to regulate genes (e.g., MMP2 and MMP-9) that are involved in metastasis-related events of prostate and breast cancer cells." (PMID 31331331, 2019). "Studies indicate that higher levels of MMP-9 correlate with higher metastasis in breast cancer patients." (PMID 31010242, 2019). "Our studies demonstrate for the first time that the function of MMP2 and MMP9 in breast cancer cell migration, which is mediated by interactions between ERα-36 and STAT3." (PMID 31409371, 2019). "For instance, KLF8 favors breast cancer cell invasion and metastasis by promoting the expression of MMP9." (PMID 31624471, 2019). "DHAvD was also tested for its ability to inhibit breast cancer cells’ invasion mediated by MMP-9 expression, whose gene promoter contains binding sites for NF-κB." (PMID 31540249, 2019). "Here, we demonstrated that AP1 and MMP9 expressions in breast cancer cells were positively correlated with the levels of CCR7 and the downregulation of CCR7 reduced the mRNA levels of MMP9 and AP1 complex (c-Fos and c-Jun)." (PMID 30781353, 2019). "Compared with the observations in the mock controls, more numbers of cells were seen in the preparations transfected with pMMP‐9‐HA, indicating that overexpression of MMP‐9 increases the invasion abilities of various breast cancer cells." (PMID 31264317, 2019). "This pathway was activated in a variety of cancers, which mediated secretion of VEGF and induction of MMP-9, and played a crucial role in regulation of breast cancer cell growth." (PMID 30728391, 2019). "In the present study, we have demonstrated for the first time that RSF EtOAc extract displayed a remarkable ability to inhibit metastasis via down regulation of MMP-2 and MMP-9 in MDA-MB-231 breast cancer cells." (PMID 31683960, 2019). "The results indicated that BA significantly decreased the expression of MMP-2 and MMP-9 secreted by breast cancer cells." (PMID 31531187, 2019). "Biomarkers as matrix metalloproteinases, a family of zinc-dependent endopeptidases, whose major members of the family are MMP-2 and MMP-9 have been related to the pathogenesis of breast cancer." (PMID 31839881, 2019). "A recombinant plasmid expressing mouse MMP‐9 was generated and transiently transfected into three different breast cancer cell lines." (PMID 31264317, 2019). "In basal-like triple negative breast cancer, MMP-9 significantly promotes breast cancer metastasis and angiogenesis." (PMID 31010242, 2019). "Added to that, these authors also showed that MMP-9 expression correlates with that of activated Stat3 in human breast cancer specimens." (PMID 31456939, 2019). "Similar effects were reported for the matrix metalloproteinases MMP-2 and MMP-9 in breast cancer, gastric cancer, colon cancer, and multiple myeloma." (PMID 31482487, 2019). "Collectively, these results suggest that MMPs are overexpressed in breast cancer tissues, and the upregulated MMP-9 and MMP-2 mRNAs are correlated with a worse prognosis." (PMID 31416219, 2019). "Here, we provide new evidences about the clinical relevance of ENO1 and MMPs (MMP-2 and MMP-9) overexpression in breast cancer tissues." (PMID 31416219, 2019). "Following activation, MMP-9 lead to degradation of type IV collagen and promoted tumor cell invasion and metastasis in breast cancer." (PMID 31744072, 2019). "The current study shows that MMP-2 and MMP-9 protein expression was significantly higher in the breast cancer than in the fibroadenoma and also in moderately differentiated breast cancer." (PMID 31839881, 2019). "Overexpression of MMP‐9 in the breast cancer cell lines increased the malignancy in vitro, which is likely associated with the activation of TGF‐β/SMAD pathway." (PMID 31264317, 2019).
breast carcinoma (continued). "We also proved that ERα-36 was also associated with STAT3 and influenced phospholyation and acetylation of STAT3, which was required for IL-6-induced MMP2 and MMP9 expression and breast cancer cell migration." (PMID 31409371, 2019). "In agreement with our results, it has been reported that nimbolide disturbs migration, invasion, and MMP-2 and MMP-9 expressions in human breast cancer cells and pancreatic cells." (PMID 31391858, 2019). "We have also noticed that MMP‐9 overexpression in breast cancer cell lines increases the transcriptions of SMADs." (PMID 31264317, 2019). "MMP-9 as an essential marker for tumor vasculogenesis and metastatic potential of cancer was highly expressed in the invasive types of breast cancer." (PMID 31387647, 2019). "As a result of CD44 cleavage, CD44 itself is one of the genes that can be transcribed as well as MMP-9 in breast cancer cells." (PMID 31331331, 2019). "The intracellular domain of CD44 (CD44-ICD) has been implicated as a co-transcription factor for RUNX2 in the regulation of expression of MMP-9 in breast carcinoma cells." (PMID 31331331, 2019). "In this study, we demonstrated that BMAL1 can promote the invasion and metastasis of breast cancer cells, and at least partially up-regulate the expression of MMP9." (PMID 31346317, 2019). "The MMP-9 activity was higher in 3D cell cultures than 2D, suggesting a high proliferative rate, survival, and invasive nature of the breast cancer cells." (PMID 30925799, 2019). "Simultaneous silencing of MMP-9 in breast cancer cells decreased the adhesiveness, invasive, migratory and wound healing characteristics of cells." (PMID 31889895, 2019). "Light microscopy showed greater concentration of stained cytoplasm for MMP-2 and MMP-9 in breast cancer in comparison to fibroadenoma." (PMID 31839881, 2019). "By inhibiting Metalloproteinase (MMP)-9, wogonin suppressed the migration and invasion of hepatocellular, breast carcinoma, and osteosarcoma cells in vitro." (PMID 31100782, 2019). "Studies by others have identified CD44 cleavage product (CD44-ICD) in complex with RUNX2 on the promoter of the MMP-9 gene in breast cancer cells." (PMID 31331331, 2019). "Regarding matrix metalloproteinases, a recent study showed that inhibition of MMP-9 by a monoclonal antibody in an immuno-competent model of HER2-positive breast cancer increased tumor-suppressive T cell infiltration and CXCR3 chemokine expression." (PMID 31482487, 2019). "This study confirmed a new mechanism by which BMAL1 up-regulated MMP9 expression to increase breast cancer metastasis, to provide research support for the prevention and treatment of breast cancer." (PMID 31346317, 2019). "It is well known that MMP9 is a downstream factor regulated by NF-κB, and NF-κB can promote breast cancer metastasis by promoting the expression of MMP9." (PMID 31346317, 2019). "Transient expression of mouse MMP‐9 in three different breast carcinoma cell lines increases the cell colony formation and migration and promotes epithelial‐mesenchymal transition (EMT)." (PMID 31264317, 2019). "The anti-migratory and anti-invasive effect of AKT1 in colorectal carcinoma cells is mediated by a decrease in MMP9 expression, as it was also observed in breast cancer cells." (PMID 31752925, 2019). "Knockdown of Osx inhibited invasion of breast cancer and osteolytic metastasis by downregulating MMP9, MMP13, VEGF, IL-8, and PTHrP, which are involved in invasion, angiogenesis, and osteolysis; overexpression of Osx had the opposite effect." (PMID 30631043, 2019). "Our results in this study also showed that IL-6 induced MMP2 and MMP9 expression in breast cancer cell and mediated cell migration." (PMID 31409371, 2019). "The proliferation rate, glucose consumed, lactate dehydrogenase (LDH), and matrix metalloproteinase 9 (MMP-9) activity of human breast cancer cells are higher in 3D constructs compared to 2D." (PMID 30925799, 2019).
breast carcinoma (continued). "We demonstrated that carnosol exerts its effect against breast cancer, at least partly, through downregulation of the activity and the expression of MMP-9, inhibition of STAT3 signaling pathway through a ROS-dependent proteasome degradation of STAT3 protein." (PMID 31456939, 2019). "Un-treated adherent breast cancer cells secreted MMP-9 higher than the detached-culture cells at a basal level." (PMID 31416203, 2019). "Light microscopy showed a higher concentration of cells with positive cytoplasmic staining for MMP-2 and MMP-9 expression in breast cancer than in fibroadenoma." (PMID 31839881, 2019). "The current study showed a higher concentration of cells with strong brown cytoplasmic staining for MMP-2 and MMP-9 in breast cancer cells than in fibroadenoma." (PMID 31839881, 2019). "It indicates that activations of TGF‐β and SMAD signal pathway in breast cancer cell line can be blocked by inhibition of MMP‐9 activity." (PMID 31264317, 2019). "MMP9 is mainly expressed in glandular epithelial tissue of the breast, so it is of great importance for studying the expression of MMP9 in breast cancer." (PMID 31346317, 2019). "Genistein shows an inhibitory effecton invasion of breast cancer cells in vitro and downregulates MMP-9 expression and upregulates TIMP-1 expression." (PMID 31359993, 2019). "Our previous study has shown that knockdown of WASF3 upregulates KISS1, a metastasis suppressor, with concomitant reduced invasion and MMP9 activity in breast cancer cells." (PMID 30867003, 2019). "In MDA-MB-231 breast cancer cells inhibition of invasion, migration, and adhesion was related to decreased matrix metalloproteinase-9 (MMP-9) activity and expression." (PMID 30893846, 2019). "Among these kinases, the secretion and activation of MMP-2 and MMP-9 in breast cancer cell lines is dependent on the cytosolic tyrosine kinases Src, and FAK." (PMID 31554180, 2019). "These discrepant effects of MMP9 seem to be consistent with its diverse expression pattern across subtypes of breast cancers, which needs further exploration." (PMID 31921385, 2019). "MMP-2 and MMP-9 had been demonstrated to be important prognostic biomarkers in diverse cancers, such as breast cancer, colorectal cancer, and NSCLC." (PMID 31827393, 2019). "ICAM, VEGF and MMP9 are useful targets in treating aggressive breast cancer, as downregulation of these genes has been previously found to suppress breast cancer cell invasion and metastasis." (PMID 30814922, 2019). "Knockdown of Osx inhibited the invasive capacity of breast cancer cells and osteolytic metastasis by downregulating MMP9, MMP13, VEGF, IL-8, and PTHrP, whereas overexpression of Osx had the opposite effect." (PMID 30631043, 2019). "Those diversity profiles of TGF‐β complexes in the breast cancer cells during overexpression of MMP‐9 deserve further study." (PMID 31264317, 2019). "BMAL1 mainly affects the expression of MMP9, which promoting the invasion and metastasis of breast cancer." (PMID 31346317, 2019). "Another study demonstrated anti-angiogenic and anti-metastatic effects of genistein by inhibiting c-erbB-2, MMP-2, and MMP-9 in breast carcinoma." (PMID 31600949, 2019). "Our data here illustrate that transient overexpression of MMP‐9 in the breast cancer cell lines strongly enhances the cellular malignant characteristics in vitro, such as the cell colony formation, migration and EMT." (PMID 31264317, 2019). "Early studies showed that both MMP-2 (gelatinase-A) and MMP-9 (gelatinase-B) can cleave Gal-3 at specific residues within its N-terminal tail (Ala62-Tyr63), leading to reduced cell surface expression in human breast cancer cell lines." (PMID 31440233, 2019). "FAK and Src contribute to the activation and secretion of MMP-2 and MMP-9, which in turn drive the cell migration and invasion phenotypes observed in in vitro models of mammary cancer cells." (PMID 31671408, 2019).
breast carcinoma (continued). "In turn, the sustained activation of down-stream MEK/ERK signalling results in increased production of the extracellular matrix (ECM)-degrading enzyme matrix metalloproteinase-9 (MMP-9) and enhanced breast cancer cell invasiveness." (PMID 30285678, 2018). "In this work, Maitake D-Fraction was shown to decrease the activity of MMP-2 and MMP-9 secreted by TNBC MDA-MB-231 cells, two MMPs clearly linked to breast cancer metastatic potential." (PMID 29805742, 2018). "To assess the specific effects of our selective inhibitors on each MMP, we utilized the MCF-7 breast cancer cell line that is naturally MMP14- and MMP9-deficient." (PMID 30174795, 2018). "In a previous study, one group of researchers investigated MMP-9 expression in normal human breast tissue and in breast cancer tissue of different molecular subtypes." (PMID 30262739, 2018). "In this study, we also provide evidence that MMP-9 is correlated with survival of patients with breast cancer; however, this is the first study that investigates the prognostic value of MMP-9 in a neoadjuvant setting." (PMID 30241470, 2018). "A codelivery therapy that inhibits HMGA2 by siRNA and acts on DNA by doxorubicin showed efficacy in CRC and the same dual treatment inhibits cell growth, vimentin (stemness marker), and MMP9 (invasion marker) in breast cancer cells." (PMID 29853899, 2018). "Here, we have objectively and simultaneously measured in situ the expression of TAM biomarkers (CD68, CD163, and the druggable target MMP-9) in two distinct breast cancer cohorts by using the validated quantitative immunofluorescence (QIF) AQUA method." (PMID 30558648, 2018). "Previous analysis of the human patient gene expression datasets revealed IL-6, CCL2, and MMP9 expression are upregulated in TNBC compared to ER+/PR+ breast cancer." (PMID 30458886, 2018). "Another study found a correlation between high expression levels of MMP-2 and MMP-9 and lymph node metastasis and tumor staging in breast cancer patients." (PMID 30518369, 2018). "The absence of multiple atypical chemokine binders such as DARC, D6, and CCX-CKR, which is associated with higher VEGF and MMP-9 expression, predicts the presence and extent of ALN metastasis in breast cancer." (PMID 30140603, 2018). "Macrophages also support breast cancer metastasis by releasing matrix degrading MMPs such as MMP-9 and angiogenic proteins such as VEGF." (PMID 30111338, 2018). "The treatment of BHMC had also reduced the expression level of MMP-9 in breast cancer cells in the present study." (PMID 29642589, 2018). "EMT-related gene expression was also reversed after was IL-6 blocked, E-cadherin was upregulated, whiles N-cadherin and MMP9 were downregulated in both breast cancer cells after IL-6 blocking." (PMID 29891854, 2018). "Despite the positive role of PKCδ in migration and invasiveness in some cellular models, it was also disclosed that PKCδ suppressed the migration and the secretion of MMP-9 in highly motile breast cancer cells." (PMID 29348560, 2018). "We examined the expression of EMT-TFs (SNAIL and TWIST) and EMT-related genes (E-cadherin, N-cadherin and MMP9) in breast cancer cells co-cultured with adipocytes by quantitative real time PCR (qtPCR)." (PMID 29891854, 2018). "It is well-known that IL-6, CCL2, and MMP9 expression are increased in TNBC compared to ER+/PR+ breast cancer." (PMID 30458886, 2018). "We thus evaluated MMP-9 expression in breast cancer cells following activated THP-1 CM treatments via Western blot analysis." (PMID 29849939, 2018). "mRNA levels of MMP2 and MMP9 were elevated in CD44 positive breast cancer cells compared to CD44-negative cells." (PMID 29747682, 2018). "In breast cancer patients, the level MMP-2 and MMP-9 are overexpressed which is associated with a shortened relapse-free survival." (PMID 30518369, 2018).